SNORA77B (small nucleolar RNA, H/ACA box 77B)
Gene: Small nucleolar RNA gene on chromosome 22 (20,126,402 to 20,126,526, forward strand). Ensembl gene ENSG00000264346.
Gene Ontology:
Biological process: RNA processing
Cellular component: nucleolus
Homologues: Orthologues: chimpanzee SNORA77B (99% identical), rat Snora77b (77% identical), mouse Gm25777 (76% identical), zebrafish SNORA77B (51% identical). Paralogues in human: SNORA77 (93% identical).